MMP9 (matrix metallopeptidase 9)
Diseases named in the same sentence as MMP9 in open-access papers (continued):
Sharing a sentence is not in itself a finding about the gene and the disease.
Granuloma (continued). "By immunostaining for MMP-9 and neutrophil elastase, we demonstrated the presence of MMP-9 secreting neutrophils in CNS-TB granulomas." (PMID 35095865, 2021). "Most of studies pay close attention to collagen breakdown and alveolar destruction mediated by MMP-1 production from Mφs, and initiation of recruitment of new monocytes to develop granuloma mediated by MMP-9 production." (PMID 35095838, 2021). "IL-17A was the highest positively correlated gene to periapical granuloma, while TLR2, TLR4, VEGF, and MMP-9 were negatively correlated with the enriched pathways of granuloma." (PMID 34539639, 2021). "Among them, MMP-1 and MMP-9 are most extensively studied owing to their roles in the creation of the granuloma and destruction of lung tissue." (PMID 35095838, 2021). "In this study we demonstrated that IL-17A and MMP-9 were expressed in the mycetoma granuloma but at different zones surrounding the grain." (PMID 31295246, 2019). "Surgical biopsies from 100 patients with confirmed mycetoma were obtained, and IL-17 and MMP-9 expression in the mycetoma granuloma were evaluated immunohistochemically." (PMID 31295246, 2019). "This reinforces the observation that myofibroblasts isolated from the granuloma tissue express MMP-9." (PMID 30273397, 2018). "In M. tuberculosis-infected mice, disruption of MMP-9 expression or activity reduces macrophage infiltration into the lungs, leading to the dysregulation of granuloma formation and reduced disease burden." (PMID 29758082, 2018). "We have demonstrated that neutrophils within granulomas express MMP-9 in the brain biopsies from patients with proven CNS-TB, further highlighting the role of MMPs in pathology of TB granulomas." (PMID 28173836, 2017). "Previous works have demonstrated increased mRNA expression levels of MMP-9 in apical granulomas in comparison to cysts, as well as MMP-9 activity levels in apical exudates from acute versus apical abscesses." (PMID 22436166, 2012). "Recent studies have shown the importance of MMP9 in interacting with Mtb secreted proteins and inducing the formation of granuloma lesions." (PMID 20824205, 2010). "TNF-deficient animals also showed continued induction of other factors important in granulomas, such as host matrix metalloproteinase 9 (MMP9), which is highly expressed in the epithelioid population of mycobacterial granulomas and is necessary for their formation and maturation." (PMID 40304497, 2025). "In sarcoidosis, it appears that pSTAT1 may promote granuloma maturation at the effector stage, while MMP-9 may be involved with promoting granuloma fibrosis." (PMID 36959923, 2023). "Moreover, stronger MMP-9 staining was found in sarcoidosis biopsies, along with smaller granulomas and less lymphocyte infiltration." (PMID 36959923, 2023). "MMP-9 has been related to tuberculosis severity and the formation of tuberculoma granulomas." (PMID 34944659, 2021). "It is therefore impossible to determine the precise function of IL-17A and MMp-9 in the formation of the mycetoma granuloma, we could only determine their presence." (PMID 31295246, 2019). "However, since we only demonstrated expression, more studies are needed to determine the roles of IL-17A and MMP-9 in the granuloma formation and to provide further insights in the mycetoma immunopathogenesis." (PMID 31295246, 2019). "Here, we evaluated an inhibitory antibody against MMP-9 as adjunctive treatment in combination with standard TB treatments in M. tuberculosis-infected C3HeB/FeJ mice, which develop well-organized, hypoxic TB granulomas as well as cavitary lesions after aerosol infection." (PMID 29758082, 2018). "In summary, we evaluated an inhibitory antibody against MMP-9 as adjunctive treatment in combination with standard TB treatments in M. tuberculosis-infected C3HeB/FeJ mice, which develop well-organized, hypoxic TB granulomas as well as cavitary lesions after aerosol infection." (PMID 29758082, 2018).
Granuloma (continued). "Similar to other forms of sarcoidosis, the expression of RUNX1, MMP9, MMP12, CCR5, ITGAX, CD44, and human leukocyte antigens (HLA) is also seen in the granuloma of CS." (PMID 40521183, 2025). "Also in mycetoma lesions both MMP-2 and MMP-9 are expressed at the site of infection, however to date there is no data indicating whether a Th17 response plays a role in the mycetoma granuloma formation and if there is a correlation between IL-17A expression and MMP expression in mycetoma lesions." (PMID 31295246, 2019). "In contrast with these results, we did not observe a significant decrease in M1 marker genes, including MMP9, NOS2, CCL2, IL-6 and ARG2, in granuloma FCMs compared with NFMs, although MMP13 and NF-κB1 levels, which are also M1-related genes, were decreased." (PMID 26197235, 2015). "Taken together, COX-2 dependent PGE2 production appears to be an important factor in driving the MMP-9 expression, a step critical for the breakdown of the ECM components during formation of granulomas." (PMID 19290049, 2009). "In addition to MMP-9, MMP-1 and -3 secretion were also found to be highly expressed in the center of granuloma which decrease towards the fibrotic, peri-granuloma region." (PMID 35095865, 2021). "In conclusion, the granuloma, the caseous necrosis, the epithelioid reaction, the microangiosis, the fibrous connective tissue, ANGPTL-4, and MMP-9 may become new supporting evidence to identify BS and TS patients." (PMID 33959835, 2021). "japonicum eggs induced a significant increase in the gene expression of the proinflammatory mediators MMP9, CCL2 (chemokine (C-C motif) ligand 2) and IL-6 (Interleukin 6), suggesting a potential role in the regulation of granuloma development via inflammatory cell recruitment and matrix remodelling." (PMID 23840855, 2013). "This supports the demonstration that myofibroblasts isolated from granuloma tissue express MMP-9 but not MMP-2, which was found to be produced by other cell types." (PMID 23840855, 2013). "Additionally, tissue localization of MMP-9 and MMP-2 was confirmed in apical granulomas by imunohistochemistry." (PMID 22436166, 2012). "To examine the induction and expression of MMP-2 and MMP-9 in experimental infectious and non-infectious murine TB granuloma models we used both a subcutaneous granuloma model for in vivo imaging in parallel with the more conventional, intranasal Mtb challenge." (PMID 29698476, 2018). "In this study, we examined existing human TB granuloma datasets in combination with infectious and non-infectious granuloma models to probe the increased expression of MMP-2 and MMP-9 in Mtb granulomas." (PMID 29698476, 2018).
keratoconus (35 papers, 2010 to 2026). A degenerative, structural disorder of the eye, characterized by a cone-shaped protrusion of the cornea. "In fact, proinflammatory cytokines (IL-1, IL-6, TNF-α, and TGF-β), oxidative stress, or degradation of collagens by metalloproteases (MMP-1, MMP-3, and MMP-9) has been implicated in keratoconus pathophysiology." (PMID 35075374, 2022). "The serum concentration of MMP-9, which plays an important role in the formation of keratoconus and has the ability to break down collagen and other extracellular matrix proteins, was found to be high in patients with OSAS." (PMID 40542209, 2025). "Increased levels of inflammatory mediators, such as immunoglobulin E (IgE), cytokines (IL-1, IL-6 and TNF-alpha) and proteolytic enzymes (MMP-9), have been found in the tears of keratoconus patients." (PMID 36138270, 2023). "Increased levels of inflammatory mediators such as IgE, cytokines (IL-1, IL-6 and TNF-alpha) and proteolytic enzymes (MMP-9) have been found in the tears of keratoconus patients." (PMID 36138270, 2023). "On the contrary, topical cyclosporine A treatment has been found to be able to reduce MMP-9 levels measured in tears with concomitant arrest of disease progression for primary keratoconus patients." (PMID 35692541, 2022). "Altered corneal epithelial and stromal expressions of specific genes, such as tumor necrosis factor-α (TNF-α), interleukin-1 (IL-1), IL-6, and matrix metalloproteinase 9 (MMP-9), were also found at the corneal cone apex in keratoconus." (PMID 35692541, 2022). "In this study, thirty-two FDA-approved ophthalmic drugs were exposed to virtual screening using docking studies against both the MMP-2 and MMP-9 proteins to find the most promising inhibitors as a proposed computational mechanism to treat keratoconus." (PMID 35684529, 2022). "As a key proteolytic enzyme in the degradation of ECM, MMP-9 levels are upregulated in tears from patients with ocular rosacea and keratoconus." (PMID 32596291, 2020). "For instance, an elevated MMP-9 is detected in the tears of subjects with ocular surface diseases such as keratoconus, ocular allergy, and DES." (PMID 31336766, 2019). "Several pro-inflammatory markers such as Interleukin-6 (Il-6) and Tnfα, along with matrix metalloproteinase 9 (Mmp9) are elevated in the tear fluid of keratoconus patients." (PMID 31569699, 2019). "Multiple studies have shown a positive correlation between MMP-9 and a multitude of diseases, such as keratoconus, herpetic keratitis, and Sjogren's syndrome, which all have an inflammatory component." (PMID 27563164, 2016). "Enzyme linked immunosorbent assay (ELISA) analysis of capillary collected tears in 28, 30 and 94 patients with keratoconus in three different studies showed elevated levels of inflammatory markers IL-6, TNFα and MMP9." (PMID 27493978, 2016). "They observed increased levels of MMP-9, tumor necrosis factor, and interleukin-6 in the tear film of patients with keratoconus and overexpression of IL-6 and TNF-alpha in the tears of subclinical keratoconic patients." (PMID 27563164, 2016). "Collier additionally notes that MMP-9 can be induced by IL-1, and others have noted that keratoconus fibroblasts release fourfold the number of these same IL-1 receptors compared to normal corneas." (PMID 21031023, 2010). "More recently, Lema and Durán targeted specific cytokines, cell adhesion molecules, and proteases in patients with keratoconus, and found levels of IL-6, TNF-α, and MMP-9 higher in keratoconus subjects as compared to normals." (PMID 21031023, 2010). "Variants in this gene can influence the production of interleukin-1 beta, a key pro-inflammatory cytokine that may contribute to the inflammatory processes and up-expression of MMP9 observed in keratoconus." (PMID 40217908, 2025). "Cyclosporine A, for instance, has been shown to suppress MMP-9 and key inflammatory cytokines in tear fluid and could potentially mitigate subclinical inflammation in keratoconus." (PMID 40980981, 2025).
keratoconus (continued). "Furthermore, this study did not measure other biochemical factors potentially involved in the pathogenesis of keratoconus, such as IL-6 and MMP-9." (PMID 40547926, 2025). "MMP-9 activity is also high in the tear fluid of patients with keratoconus." (PMID 33470337, 2021). "MMP9 (matrix metallopeptidase 9), as one of imperative matrix metalloproteinase, synthesized by corneal epithelial cells and stromal cells, have long been suspected of having a significant role in keratoconus." (PMID 32016117, 2020). "The ocular surface inflammation is activated by proteases, including MMP-9, and based on our study it may help to differentiate between keratoconus and pellucid marginal degeneration." (PMID 27074131, 2016). "Changes in MMP-9 are often noticed in people with keratoconus, and it would be interesting for future researchers to investigate whether MMP-9 could be utilized as a precursor for the early detection of pre-keratoconic patients to halt the progression of corneal epithelium disruption." (PMID 41009673, 2025). "It would stand to reason that MMP-9 could indeed be overexpressed in keratoconus." (PMID 21031023, 2010). "Matrix metalloproteinases (especially MMP-9 and MMP-13) are often upregulated in keratoconus; these enzymes cleave collagens and basement membrane components." (PMID 41595486, 2026). "It is notable that elevated levels of matrix metalloproteinase-9 (MMP-9) have been observed in the tears, corneal tissues, and serum of keratoconus patients." (PMID 40547926, 2025). "Partly in line with these results, increased tear levels of MMP-1, MMP-3, MMP-7, MMP-9, and MMP-13; IL-4, IL-5, IL-6, and IL-8, and TNF-α, -β were found in keratoconus." (PMID 26881061, 2016). "Recent studies have suggested pro-inflammatory factors as key to keratoconus pathogenesis based on their findings of elevated interleukin (IL)-6, tumor necrosis factor (TNF)-α and matrix metalloproteinase (MMP)-9 in the tear fluid of keratoconus patients." (PMID 21298010, 2011). "Elevated levels of interleukin- (IL-) 1b, IL-4, IL-5, IL-6, IL-8, and IL-17; tumor necrosis factor (TNF)-α, -β; interferon- (IFN-) γ; matrix metalloproteinase- (MMP-) 1, MMP-3, MMP-7, MMP-9, and MMP-13; Cathepsin B; and Lipocalin-1 have been found in the tears of patients with keratoconus." (PMID 26881061, 2016). "In the current study, we have determined the associations between nine mediators (IL-6, IL-10, CXCL8/IL-8, CCL5/RANTES, MMP-9, MMP-13, TIMP-1, t-PA, and PAI-1) in the tear fluid of keratoconic patients covering the whole spectrum of the disease (from subclinical to manifest keratoconus)." (PMID 26881061, 2016). "Therefore, accumulated information about these markers should be considered for application in diagnosis e.g., elevated MMP9 and IL6 along with a reduction in markers such as LOX, SFRP1 in tears can give a specific diagnosis of keratoconus." (PMID 27493978, 2016). "Keratoconus, with a similar inflammatory profile to that of ocular surface disease, has elevated Interleukin (IL)-1β, IL-6, tumor necrosis factor (TNF)-α, and matrix metalloproteinase (MMP)-9, contributing to extracellular matrix degradation and stromal thinning." (PMID 40993744, 2025). "Differential gene expression analysis in debrided corneal epithelia of patients with keratoconus showed dysregulations of LOX and collagens - collagen I alpha 1 (COLIA1) and collagen IV alpha 1 (COLIVA1) and an elevated expression of matrix metalloproteinase 9 (MMP9)." (PMID 27493978, 2016). "Our study population did not include anyone with keratoconus, and thus our hay fever group may not have yet progressed to such a severe epithelial tight junction disruption, as demonstrated by non-significant MMP-9 levels between the hay fever and healthy control groups." (PMID 41009673, 2025).
esophageal cancer (34 papers, 2009 to 2025). A primary or metastatic malignant neoplasm involving the esophagus. "The goal of this research was to analyze the SERPINE1 -675 (rs1799889) and MMP9 T-1702A (rs3918241) polymorphisms in Esophageal Cancer." (PMID 34660916, 2021). "The goal of this research was to analyze the SERPINE1 -675 4G/5G (rs1799889) and MMP9 T-1702A (rs2297864) polymorphisms in esophageal cancer among polish patients, classified as part of the Caucasian population." (PMID 34660916, 2021). "A positive correlation between miR-134 expression and matrix metalloproteinase-9 (MMP-9) exists in esophageal cancer, and high expression in tumors is associated with shorter survival time." (PMID 32258065, 2020). "Overexpression of VEGF-C and MMP-9 and positive association with advanced esophageal cancer and invading ESCC cells (Gene Expression Omnibus (GEO): GSE21293)." (PMID 31824776, 2019). "A study of esophageal cancer showed that MMP-9 might regulate tumour-associated macrophages." (PMID 36324509, 2022). "Our previous studies have shown that TNF-α regulates the migration of cancer cells, including esophageal cancer, by affecting the expression of MMP9." (PMID 36555705, 2022). "Here, we found that lactate can also enhance the promigratory effect of TNF-α in esophageal cancer cells by intensifying TNF-α-related MMP9 expression, and the use of SO stopped this activity." (PMID 36555705, 2022). "Studies have shown that the expression of GST family enzymes and MMP9 are early events in the development of esophageal cancer." (PMID 35048517, 2022). "At last, 12 associations (MMP-2 rs243865 with esophageal cancer and LC, MMP-7 rs11568818 with bladder and CC, and MMP-9 rs3918242 with BC) were rated as strong evidence for cancer risk, 7 as moderate evidence, and 15 as weak." (PMID 35574300, 2022). "We revealed for the first time that LDHA inhibition blocks TNF-α-induced migration of esophageal cancer cells and effectively inhibits MMP9 expression in cells stimulated with TNF-α by attenuating activation of the ERK1/2-related signaling pathway." (PMID 36555705, 2022). "In order to demonstrate the mechanism of QGS inhibiting cell mobility of ESCC cells, We also studied two protein pathways in which MMP2 and MMP9, these are closely related to esophageal cancer infiltration and metastasis." (PMID 31110076, 2019). "This experiment also showed that QGS inhibits the migration of esophageal cancer cells by affecting p65 phosphorylation and inhibiting the expression of MMP9." (PMID 31110076, 2019). "The increasing transcriptional activity of MMP9 contributes to the invasion and metastasis of esophageal cancer." (PMID 30704487, 2019). "In cell experiments, the IL-6 silencing vector induced both an increase in E-cadherin levels in esophageal cancer cells, and decreases in MMP-9 levels." (PMID 23561329, 2013). "Finally, 12 associations (MMP-2 rs243865 with esophageal cancer risk and LC risk, MMP-7 rs11568818 with bladder risk and CC risk, and MMP-9 rs3918242 with BC risk) were rated as strong evidence, 7 as moderate evidence, and 15 as weak." (PMID 35574300, 2022). "Thus, UA potentiates the inhibitory effect of PTX on cell invasion and metastasis in esophageal cancer cells by targeting uPA, MMP-9, and E-cadherin." (PMID 34768915, 2021). "Moreover, CDH1 was confirmed to repress the levels of the matrix metalloproteinase 2 (MMP2) and MMP9 in Esophageal cancer." (PMID 32714095, 2020). "According to these findings it was suggested that CSCs in esophageal cancer may release PLGF to promote cancer metastasis through MMP9 activation." (PMID 28930282, 2017). "Therefore, the purpose of this work was to address the question of whether inhibition of LDHA activity may affect the pro-migratory effects of TNF-α in esophageal cancers, with particular attention to the role of MMP9." (PMID 36555705, 2022).